FTO (FTO alpha-ketoglutarate dependent dioxygenase)
Diseases named in the same sentence as FTO in open-access papers (continued):
Sharing a sentence is not in itself a finding about the gene and the disease.
gastric cancer (continued). "Moreover, compare with low risk group patients, gastric cancer patients generally contain a higher proportion of FTO, lower proportion of ALKBH5 and RBM15 in the high risk group." (PMID 31681576, 2019). "Additionally, FTO’s activity promotes the degradation of vesicle-associated membrane protein-1 mRNA, affecting mitochondrial dynamics and metabolic functions, and contributing to the progression of gastric cancer." (PMID 39192357, 2024). "Moreover, Cox regression analyses indicated that m6A risk model score was a prognostic factor for OS and FTO upregulation might be a potential independent prognostic factor for recurrence-free survival (RFS) in gastric cancer patients." (PMID 32226518, 2020). "Moreover, FTO is higher expressed in high risk scores subtype in gastric cancer." (PMID 31681576, 2019). "FTO has been shown to augment the proliferation and metastasis of gastric cancer by modulating mitochondrial fission/fusion dynamics and metabolic processes, which involves the facilitation of caveolin-1 mRNA degradation via demethylation." (PMID 39869517, 2025). "Strikingly, silence of MIDN upregulated FTO protein expression in both breast and gastric cancer cells." (PMID 40002690, 2025). "Studies have shown that FTO is overexpressed in gastric cancer and that its demethylase activity upregulates CDKAL1, which promotes cell proliferation and mitochondrial fusion, thereby increasing the resistance of gastric cancer to chemotherapy with 5-Fu." (PMID 41584846, 2025). "Another study reported that FTO augmented gastric cancer metastasis by upregulating ITGB1 via decreasing its m6A levels." (PMID 40002690, 2025). "Small-molecule inhibitors of FTO have also shown promise in gastric cancer, allowing the increase in m6A levels and regulating Wnt/PI3K-Akt signaling." (PMID 41228380, 2025). "The silence of FTO alleviated the resistance of gastric cancer cells to cisplatin via blocking ULK1-related autophagy." (PMID 40002690, 2025). "We further apply pum6a to study the dynamic regulation of m6A demethylases in gastric cancer under hypoxia, revealing distinct roles for FTO and ALKBH5 in modulating m6A modifications and uncovering key insights into m6A -mediated transcript stability." (PMID 39824841, 2025). "Recent studies showed that FTO promotes stem-like properties and lymph node metastasis in gastric cancer, while its knockdown suppresses proliferation, migration, and invasion." (PMID 41228380, 2025). "FTO enhanced the proliferation and metastasis of gastric cancer cells via potentiating caveolin-1 mRNA degradation." (PMID 40002690, 2025). "These dual roles in tumor progression and immune evasion position FTO as both a critical prognostic indicator for improving gastric cancer management." (PMID 40986143, 2025). "FTO affects the proliferation, migration, and invasion of gastric cancer cells by inhibiting caveolin-1, a protein that also regulates mitochondrial dynamics and metabolism in these cells." (PMID 39791162, 2025). "For instance, FTO has been reported as an oncogene in metastatic endometrial carcinoma, gastric cancer, bladder cancer, hepatocellular carcinoma, or acute myeloid leukemia; however, it also acts as an anti-oncogene in gastric cancer." (PMID 39744011, 2024). "In our study, data from TCGA and clinical samples showed that FTO was highly expressed in gastric cancer tissues." (PMID 38556586, 2024). "FTO knockdown in cisplatin-resistant gastric cancer cells (SGC-7901/DDP) inhibits ULK1-mediated autophagy and reverses cisplatin resistance both in vivo and in vitro." (PMID 38576024, 2024). "In vitro and in vivo experiments confirmed the role of FTO in promoting gastric cancer cell proliferation." (PMID 38556586, 2024). "For example, FTO promotes growth and metastasis of gastric cancer via metabolic regulation of mitochondrial dynamics." (PMID 38549713, 2024).
gastric cancer (continued). "The m6A eraser oncogenes (such as Fat mass and obesity-associated protein termed as FTO) have found to be upregulated in gastric cancer tissues, and this expression of FTO has been detected to play crucial role in differentiation and lymph node metastases." (PMID 38966068, 2024). "One recent study consistently showed that the deletion of m6A demethylase FTO depletion induces mitochondrial fission in gastric cancer cells via caveolin-1." (PMID 38549713, 2024). "The m6A modified demethylase FTO affects the progression of gastric cancer (GC), and the role mechanism of FTO in GC is still unclear." (PMID 38200441, 2024). "The objective of this study was to validate the role of FTO in promoting gastric cancer (GC) progression and evaluate the relationship between FTO expression and overall survival (OS) of GC patients." (PMID 38200441, 2024). "It has been reported that FTO can reduce the methylation of MYC in gastric cancer cells and stabilize its expression, ultimately resulting in augmented proliferation, migration and invasion of gastric cancer cells in vitro." (PMID 39744011, 2024). "FTO was elevated in gastric cancer and showed an oncogenic effect by promoting cell proliferation and metastasis via inducing the degradation of caveolin-1 (CAV1) mRNA by demethylation." (PMID 38503745, 2024). "Studies have shown that in cisplatin-resistant gastric cancer cells, the expression level of FTO is significantly increased, while the level of m6A in total RNA is significantly decreased." (PMID 38576024, 2024). "In the context of gastric cancer, the expression of demethylase genes, FTO and ALKBH1, holds prognostic significance, possibly indicating their involvement in autophagy regulation." (PMID 38148841, 2023). "As previously reported, the expression of FTO is elevated within tumors, which enhances gastric cancer proliferation, migration, and lymph node metastasis." (PMID 36718644, 2023). "Consistently, METTL14 knockdown promoted gastric cancer cell growth, whereas FTO knockdown (m6A upregulation) reversed the malignant phenotypes." (PMID 36977668, 2023). "Many kinds of cancers, including human cervical squamous cell carcinoma tissue and stomach cancer, have high levels of FTO, while bladder cancer has considerably lower expression of FTO levels compared to neighboring normal tissues." (PMID 37444576, 2023). "FTO can induce autophagy in various tumor tissues and cell lines, including gastric cancer, ovarian cancer, and renal cell carcinoma." (PMID 36632456, 2023). "A study published in 2017 has demonstrated that FTO was highly expressed in gastric cancer cell lines and correlated to poor prognosis in patients with gastric cancer." (PMID 35628623, 2022). "Knockdown of FTO reversed cisplatin resistance of gastric cancer cells both in vitro and in vivo, which was attributed to the inhibition of ULK1-mediated autophagy." (PMID 36246528, 2022). "In gastric cancer, abnormal expression of FTO correlates with the progression and metastasis of gastric cancer." (PMID 34660577, 2021). "Omeprazole pretreatment promoted the total m6A level of gastric cancer cells due to the FTO inhibition induced by omeprazole." (PMID 33393595, 2021). "Experimental data have shown that FTO in a low expression state has the ability to inhibit the proliferation, migration, and invasion of gastric cancer." (PMID 34149432, 2021). "Similarly, decreased m6A methylation due to decreased METTL3 and increased FTO was also associated with increased tumorignesis in gastric cancer (GC)." (PMID 33814008, 2021). "Our results suggested that FTO promoted survival-promoting autophagy of gastric cancer cells, at least in the context of the present study." (PMID 33393595, 2021). "FTO is highly expressed in many types of cancer such as human cervical squamous cell carcinoma tissue and gastric cancer." (PMID 34499008, 2021).
gastric cancer (continued). "In gastric cancer, reduced m6A modification can promote gastric cancer malignancy by activating oncogenic signalling, and FTO acting as an oncogene can promote tumour growth." (PMID 32898471, 2020). "Based on this finding, we derived a risk signature, using 3 m6A RNA methylation regulators (FTO, RBM15, ALKBH5), that is not only an independent prognostic marker but can also predict the clinicopathological features of gastric cancer." (PMID 31681576, 2019). "Consistent with the function of FTO in drug resistance, it was reported that overexpression of FTO is a marker for poor prognosis in cancers such as gastric cancer and endometrial carcinoma." (PMID 30105001, 2018). "It was also reported that the depletion of FTO expression significantly inhibited cell proliferation, migration, and invasion of human gastric cancer cell lines, and the opposite phenomenon was observed when FTO was forced expressed." (PMID 30105001, 2018). "Studies have found that FTO is highly expressed in gastric cancer tissues." (PMID 40332101, 2025). "Finally, Zhu's meta‐analysis on FTO expression in gastric cancer investigated clinical pathological features and prognosis, emphasizing the broader role of FTO beyond genetic polymorphisms." (PMID 40391584, 2025). "The knockdown of FTO inhibits the proliferation, migration, and invasion of gastric cancer cells." (PMID 40332101, 2025). "Additionally, the role of FTO as an m6A demethylase in gastric cancer has been explored, showing higher FTO levels in tissues, particularly in cases with liver metastases." (PMID 39791162, 2025). "In addition, in cisplatin-resistant gastric cancer cells, m6A methylated RNA levels are significantly reduced, while FTO expression is increased." (PMID 41584846, 2025). "Demethylases such as ALKBH5 and FTO also reshape cytokine networks in gastric cancer." (PMID 41228380, 2025). "For example, in digestive system tumors, it has been revealed that FTO exhibits significant expression in gastric cancer, and it promotes the initiation and progression of gastric cancer by augmenting the proliferation, migration, and lymphatic metastasis of gastric cancer cells." (PMID 39820532, 2025). "Inhibiting the FTO gene diminishes the stemness of gastric cancer cells, and inhibiting FTO may provide a viable therapeutic strategy for patients with metastatic gastric cancer." (PMID 40110193, 2025). "In gastric cancer, FTO has been identified as a potential target for cisplatin resistance." (PMID 38576024, 2024). "The role of FTO in the progression of gastric cancer has been widely investigated; however, the role of ALKBH4 remains unclear." (PMID 38902235, 2024). "Therefore, our study demonstrated that FTO promoted gastric cancer proliferation through the circFAM192A/SLC7A5 axis in the m6A-dependent manner." (PMID 38556586, 2024). "Furthermore, FTO inhibits mTORC1, a negative regulator of autophagy, and promotes pro-survival autophagy, ultimately leading to chemoresistance in gastric cancer." (PMID 38576024, 2024). "Our study shed new light on the role of FTO in gastric cancer progression." (PMID 38556586, 2024). "Finally, the FTO expression changes and m6A expression levels were further validated in clinical gastric cancer tissues." (PMID 36918410, 2023). "Combined effect of LncRNA AC026691.1 and FTO might suppress gastric cancer via downregulation of m6A level." (PMID 37365581, 2023). "FTO is highly expressed in gastric cancer and negatively correlated with patient survival." (PMID 37511932, 2023). "Finally, we argue a strong link between FTO and gastric cancer, further suggesting the involvement of FTO in the malignant transformation of normal gastric epithelium and even in the development of tumorigenesis." (PMID 36918410, 2023).
gastric cancer (continued). "In gastric cancer tissues, Western blot revealed that the expression level of FTO and CD44 was significantly higher than that of adjacent tissues, and in immunohistochemistry, FTO expression was significantly elevated in GC patients, with positive staining mainly concentrated in GC cell nuclei." (PMID 36918410, 2023). "FTO is also involved in the proliferation, invasion and metastasis of gastric cancer cells, and has excellent prognostic value.m6A modifications are involved in the regulation of tumor stem cells (CSC) and tumor immune microenvironment leading to malignant phenotypes." (PMID 36918410, 2023). "However, FTO can reduce the methylation of c-Myc in gastric cancer cells and stabilize its expression, thereby affecting the tumor initiation activity of gastric cancer cells." (PMID 35022030, 2022). "However, in gastric cancer cells, inhibition of m6A methylation can activate Wnt signaling pathway to promote tumor cell proliferation and invasion, while FTO knockout can reverse these molecular and behaviors changes." (PMID 35022030, 2022). "The results showed that RBM15 (HR = 0.69, 95% CI = 0.52–0.92), FTO (HR = 1.46, 95% CI = 1.09–1.96), MSI2 (HR = 0.75, 95% CI = 0.58–0.97) and ZC3H7B (HR = 0.70, 95% CI = 0.53–0.93) was associated with prognosis in gastric cancer patients and the RiskSscore model was established." (PMID 36003776, 2022). "Similarly, some studies have shown that the expression of FTO is related to the occurrence and prognosis of gastric cancer." (PMID 34149432, 2021). "However, high expression of FTO exerts an opposite result, which promotes the activity of gastric cancer cells." (PMID 34149432, 2021). "Previous studies reported that elevated m6A levels of peripheral blood in patients with gastric cancer might be due to downregulation of FTO and ALKBH5, which belonged to “erasers”." (PMID 34659267, 2021). "According to the evidence, FTO was correlated with the malignancy of gastric cancer." (PMID 31681576, 2019). "Additionally, the study found that the expressions of two m6A demethylases, ALKBH5 and FTO, were substantially suppressed in both in vitro and in vivo samples, suggesting a possible correlation between elevated m6A levels and the development of gastric cancer." (PMID 39009956, 2024). "Importantly, LncRNA AC026691.1 could inhibit both migration and proliferation of gastric cancer through FTO demethylation." (PMID 37365581, 2023). "FTO could be a helpful therapeutic target for gastric cancer patients." (PMID 36003776, 2022). "Collectively, FTO may be an epigenetic modification target for the treatment of gastric cancer." (PMID 35628623, 2022). "The FTO oncogenic role was also reported in human gastric cancer (GC), where FTO was upregulated on both protein and mRNA levels." (PMID 35409166, 2022). "Moreover, FTO also be found that in the gastric cancer’s progression and metastasis." (PMID 34476213, 2021). "Hence, FTO is an important molecular marker for the diagnosis and prognosis of gastric cancer." (PMID 34660577, 2021). "The m6A RNA modifications and their regulators—including METTL3, ALKBH5, FTO, YTHDFs, hnRNPA2B1, and IGF2BP2—have particularly emerged as key drivers of chemotherapy resistance in gastric cancer." (PMID 41228380, 2025). "The dynamic regulation of m6A modifications by demethylases FTO and ALKBH5 under hypoxia plays a critical role in the adaptation of gastric cancer cells to oxygen-limited environments." (PMID 39824841, 2025). "In gastric cancer, global dysregulation of the m6A machinery has also been documented, with METTL3, FTO, YTHDFs, IGF2BPs and hnRNPA2B1 frequently upregulated in patient tissues and associated with poor prognosis, advanced stages and metastasis." (PMID 41228380, 2025). "High expression of METTL3, METTL14, FTO, YTDHF1-2 and IGF2BP1, in gastric cancer, facilitates tumor immune evasion by maintaining the stability and expression of PD-L1 transcripts." (PMID 41228380, 2025).
gastric cancer (continued). "We found that in 10 pairs of human gastric cancer and normal tissues, ALKBH1, ALKBH4, ALKBH8, and FTO were highly expressed in the gastric cancer tissues." (PMID 38902235, 2024). "The activity of HDAC3 maintains the standard transmission of the FTO/m6A/MYC signaling pathway, thereby influencing the development of gastric cancer." (PMID 39192357, 2024). "Suppression of m6A via METTL14 depletion promoted gastric cancer (GC) cell proliferation through activating Wnt and PI3K-AKT signaling pathways, while upregulation of m6A due to FTO depletion reversed these phenotypical and molecular signaling changes." (PMID 37015927, 2023). "FTO accelerated cell growth and metastasis via regulation of caveolin-1 and ITGB1 and metabolic regulation of mitochondrial dynamics in gastric cancer." (PMID 36003776, 2022). "Four genes, RBM15, FTO, MSI2 and ZC3H7B were identified as influencing the prognosis of gastric cancer patients in univariate analysis of 24 regulators." (PMID 36003776, 2022). "It has been shown that Unc-51-like kinase 1 (ULK1) expression was regulated in an FTO-m6A-dependent and YTHDF2-mediated manner in gastric cancer." (PMID 36246528, 2022). "Similarly, NAD+ levels and the NAD+/NADH ratio were significantly decreased under hypoxia following demethylases knockdown, suggesting that FTO and ALKBH5 are key regulators of energy homeostasis in gastric cancer cells." (PMID 39824841, 2025). "However, ALKBH8 was highly expressed in only six pairs of gastric cancer tissues, while ALKBH4 was highly expressed in seven pairs, and FTO was highly expressed in all 10 pairs." (PMID 38902235, 2024). "Evidently, FTO’s role in gastric cancer can be both positive and negative, depending on the specific molecular and pathological context." (PMID 39744011, 2024). "RNA demethylase FTO promotes gastric cancer tumorigenesis and progression via the SP1-AURKB-ATM signaling pathway, shedding new light on the diagnoses and treatments for gastric cancer patients." (PMID 38956367, 2024). "In gastric cancer, FOXA2-mediated FTO stabilizes MYC mRNA by reducing m6A methylation of MYC." (PMID 37932821, 2023). "Similarly, our study found that m6A levels were altered in both malignantly transformed gastric epithelial cells and gastric cancer tissues, and CD44 was positively correlated with the expression level of FTO." (PMID 36918410, 2023). "Knockdown of FTO increases the level of 6mA which promotes cell proliferation and invasion by activating PI3K (Phosphatidylinositol-3-kinase) signaling in gastric cancer and increases lung squamous cell growth and invasiveness by inhibiting the cell apoptotic genes." (PMID 35923209, 2022). "FTO expression was reported to have important roles in promoting gastric cancer occurrence and could be an vital molecular marker in the diagnosis and prognosis of GC patients." (PMID 33393595, 2021). "The results indicated that high expression of FTO (HR = 1.15, 95% CI = 1.02–1.29), HNRNPC (HR = 1.09, 95% CI = 1.02–1.18), YTHDC2 (HR = 1.22, 95% CI = 1.07–1.42), and WTAP (HR = 1.18, 95% CI = 1.02–1.33) have a worse survival in patients with gastric cancer." (PMID 31681576, 2019). "The m6A modification of its downstream gene ULK1 can be removed by FTO, thus protecting it from targeted degradation by YTHDF2 and playing a role in cisplatin resistance in gastric cancer (GC)." (PMID 39468015, 2024). "M6A “eraser” related gene including FTO and ALKBH5 were found to be a reliable prognostic and predictive tool in a recent study of 738 gastric cancer (GC) samples obtained from two independent datasets." (PMID 39009956, 2024). "Thirdly, we hypothesize that FTO and ALKBH5 serve as “m6A erasers” to regulate gastric cancer." (PMID 33718213, 2021). "Although ITGB1 and LAMC1 were both tightly related to the prognosis of gastric cancer, it was suggested that LAMC1 might be involved in a more complex molecular mechanism, rather than being directly regulated by FTO." (PMID 34277426, 2021).